INS (insulin)
Diseases named in the same sentence as INS in open-access papers (continued):
Sharing a sentence is not in itself a finding about the gene and the disease.
Hypoglycemia (continued). "In addition, the incidence of severe hypoglycaemia has been reduced by continuous subcutaneous insulin infusion (CSII) therapy." (PMID 33227006, 2020). "Interestingly, the effect of compound 1 on insulin secretion was similar to that of the oral sulfonylurea drug, gliclazide, that induces hypoglycemia, at a concentration of 10 μM." (PMID 32847055, 2020). "Among NON DM and IFG subjects, RVO incidence increased along with the BMI, but in all MED DM subjects, those with a DM duration of less than 5 years and more than 5 years who had been using insulin or oral hypoglycemia medications at baseline, RVO incidence decreased as BMI increased." (PMID 32601344, 2020). "The criteria advice is to avoid using insulin sliding scale with short- or rapid-acting insulin without concurrent use of basal or long-acting insulin to minimize the risk of hypoglycemia." (PMID 33233330, 2020). "Exercise increases absorption rates of some, but not all forms of insulin, which can exacerbate the risk for hypoglycaemia." (PMID 32533229, 2020). "Results from preliminary work (data not shown) indicate that 50 μL of whole blood would be sufficient to perform a full hypoglycemia panel consisting of insulin, cortisol, growth hormone, glucose, beta hydroxybutyrate, and free fatty acids as the sample utilized for each assay is about 1 μL." (PMID 31906315, 2020). "In addition, studies report an improvement in QoL (satisfaction with treatment) and symptoms of hypoglycemia in patients using an insulin infusion pump compared to those using multiple doses of insulin (three to four times a day)." (PMID 32187271, 2020). "In conclusion, sotagliflozin treatment decreased not only the HbA1c levels and insulin dose but also the body weight without causing hypoglycemia in patients with T1D." (PMID 32973680, 2020). "Of note, studies have shown that a dietary fiber diet may reduce hypoglycemia by regulating the gut microbiota to reduce insulin secretion." (PMID 32867177, 2020). "If hypoglycemia persists, acarbose is the preferred medical option as it slows the absorption of glucose into the blood stream, thus avoiding a glycemic peak followed by insulin release." (PMID 32185602, 2020). "Moreover, in the future, automated insulin delivery systems promise tighter glucose control with less hypoglycemia and lower burden of care for youth with T1D and their families." (PMID 32733375, 2020). "In addition, elderly patients have decreased kidney and liver metabolic function and poor drug clearance and are hence prone to hypoglycemia during intensive insulin therapy." (PMID 33015194, 2020). "Insulin delivery suspension when reaching a low glucose level or in prediction of a low glucose level has demonstrated significant reduction in hypoglycemia exposure." (PMID 31953687, 2020). "This is not only inconvenient for most people but can also increase the risk of hypoglycemia both before and after a meal if the insulin injection is not timed appropriately for the meal." (PMID 32396624, 2020). "Notably, however, insulin levels at the time of hypoglycemia remain the gold standard for diagnosing HH." (PMID 33133020, 2020). "For youth with T1D, many factors need to be taken into consideration before engaging in physical activity such as starting glucose level, timing and intensity of activity, insulin dosing, carbohydrate supplementation, exercise time of day, individual fitness, and prior episodes of hypoglycemia." (PMID 32733375, 2020). "At that time, researchers raised concerns that the beneficial effect of aggressive insulin therapy might have been related to a disproportionate use of parenteral nutrition and iatrogenic hypoglycemia." (PMID 32265626, 2020). "At least 12 genetic defects have been identified that result in dysregulated and increased insulin secretion and subsequently severe hypoglycemia, which may be transient or persistent." (PMID 33275114, 2020).
Hypoglycemia (continued). "Sik3-/- mice display lipodystrophy, hypolipidemia, hypoglycemia, and hyper-insulin sensitivity." (PMID 31978080, 2020). "An objective and simple clinical prediction rule may help guide more appropriate insulin dose setting and hypoglycemia prevention." (PMID 33015194, 2020). "Pooled data from 15 randomized treat-to-target trials in patients treated with basal insulin found that titrating basal doses above 0.5 units/kg did not result in further HbA1c or fasting plasma glucose improvement and increased the risk of hypoglycemia." (PMID 31833010, 2020). "The glucose-dependent secretion of insulin reduces the probability of hypoglycemia, which makes GPR40 an excellent target for developing therapies that could be efficacious with fewer side effects." (PMID 32850735, 2020). "In addition to the pain, the gap between glucose monitoring and insulin dosage, combined with the delayed absorption of subcutaneously injected insulin, limits blood glucose control and can lead to hypoglycemia." (PMID 32325974, 2020). "However, these are often accompanied by weight gain and/or hypoglycemia, and results should be interpreted within the context of total insulin doses used." (PMID 33425548, 2020). "Furthermore, the effect of RFRP-3 reduced insulin-induced hypoglycemia lasted longer in rats treated with chronic doses of RFRP-3 than those treated with acute doses." (PMID 32328034, 2020). "Nevertheless, older people using insulin and SUs should be regularly reviewed, particularly in relation to hypoglycemia which may be under reported in older people as they can developed blunted awareness." (PMID 32256448, 2020). "Insulin, SU, and alcohol are common causes of drug-induced hypoglycemia, but hypoglycemia occurs in around 10% of cases without the use of these drugs." (PMID 32518665, 2020). "In the trial comparing cardiovascular safety of insulin degludec vs. insulin glargine in patients with type 2 diabetes at high risk of cardiovascular events (DEVOTE), higher day-to-day fasting GV was associated with all-cause mortality and severe hypoglycemia." (PMID 33217980, 2020). "It has been suggested that the speed of intensification together with the levels of insulin and thiazolidinediones used compared to the control arm, may have heightened CVD risk following weight gain and excess hypoglycemia." (PMID 32256448, 2020). "Our research plan involved the pretreatment of male rats by icv delivery of the α1-AR reverse-agonist prazocin (PRZ) or vehicle ahead of induction of a single versus final episode (e.g., occurring on the fourth consecutive day of insulin administration) of hypoglycemia." (PMID 32188013, 2020). "Insulin and C-peptide were suppressed at the time of hypoglycemia." (PMID 32393233, 2020). "However, HH patients experience dysregulated insulin secretion, which leads to recurrent hypoglycemia." (PMID 33133020, 2020). "This can lead to a reduced glucagon response to insulin-induced hypoglycemia." (PMID 33042003, 2020). "In addition, it was reported that Gla-300 has lower possibility of hypoglycaemia than Gla-100 and insulin degrudec." (PMID 32005949, 2020). "Because the decrease in insulin level was found to correspond to that of blood glucose level, this alteration of blood insulin is possibly due to decreased insulin secretion in response to anesthesia-induced hypoglycemia in neonatal mice." (PMID 32240260, 2020). "For example, anticipatory signals increase insulin release upon food consumption but before any changes in blood glucose, and neural signals suppress insulin and stimulate glucagon release to counteract hypoglycemia." (PMID 33036983, 2020). "The stimulation of insulin secretion in such a situation induces deleterious hypoglycemia." (PMID 32143698, 2020).
Hypoglycemia (continued). "Therefore, the normal metabolic pathway changes and the NEFA produced by fat mobilization is incompletely oxidized to produce acetoacetate and BHBA, causing BHBA to accumulate, and type I cows usually have hypoglycemia, low INS, high BHBA, and high NEFA." (PMID 32054179, 2020). "Overall, 66.0% of the users (n = 696) were satisfied with the insulin pumps, especially the operation (n = 129, 18.7%), the hypoglycemia switch-off (n = 108, 15.6%), the size or weight (n = 88, 12.7), possible CGM connection (n = 87,12.6), and tubeless function (n = 68, 9.8%)." (PMID 33332410, 2020). "The patient was diagnosed with hyperinsulinism because of the following findings: measurable insulin during hypoglycemia, low blood ketones during hypoglycemia, the requirement of high carbohydrate intake to achieve euglycemia and hypoglycemic episodes during continuous tube feeding." (PMID 32373468, 2020). "A steep drop in insulin-induced hypoglycemia excites the hypothalamic-pituitary-adrenal axis, finally leading to the secretion of two hormones – adrenaline and cortisol (corticosterone in rodents) – which oppose insulin action and re-establish normoglycemia." (PMID 32378377, 2020). "However, with most prolonged exercise events, late-onset hypoglycaemia remains common for athletes and, thus, basal insulin-dose reduction and/or bedtime snack strategies are recommended." (PMID 32533229, 2020). "Because there are differences in the physiological responses to repeated glucose deprivation with 2DG versus repeated insulin-induced hypoglycemia, we assessed GHRH neuron activation, dendritic spine number, inhibitory inputs, and plasma GH in response to repeated insulin-induced hypoglycemia." (PMID 33148883, 2020). "This could be due to fear of hypoglycemia, or insufficient skills to adjust insulin dosage at a time of pregnancy when insulin needs may increase rapidly." (PMID 32346630, 2020). "Hypoglycemia occurred in one patient treated with exenatide and five patients treated with insulin." (PMID 32334592, 2020). "Thus, intranasal, and other direct CNS infusion methods, avoid the potential complication of insulin induced hypoglycemia seen with intravenous (IV) infusion." (PMID 33100956, 2020). "For example, patients with comorbidities that could interfere with study outcomes, patients living too far from the study site, or patients who were unable to manage insulin and cope with hypoglycaemia were excluded." (PMID 32188470, 2020). "Among the remaining 33 patients, 15 patients (14 in the conventional group and 1 in the optimized group) achieved adequate hypoglycemia while 18 patients (14 in the conventional group and 4 in the optimized group) still failed after being given a repeated dose of insulin." (PMID 32328036, 2020). "The abuse of insulin in cases of factitious hypoglycemia may be comparably easy due to the possibility of detection in the laboratory, whereas a patient presenting with factitious fever may require an extensive and multidisciplinary investigation." (PMID 32524413, 2020). "Metformin is a drug that can achieve tight glucose control without the added risk of hypoglycemia like insulin." (PMID 31915055, 2020). "Hypoglycaemia is a common complication of insulin therapy, including inhaled insulin." (PMID 32785196, 2020). "Congenital hyperinsulinism (CHI) causes dysregulated insulin secretion which can lead to life‐threatening hypoglycaemia if not effectively managed." (PMID 31577849, 2020). "In summary, this experimental rat model of insulin-induced hypoglycaemia on foetal skeletal development shows pronounced effects on growth plate organisation; however, discontinuation of insulin-infusion after organogenesis allows for a partly normal development." (PMID 32221393, 2020). "In addition, exposed F0 showed normal latency to reach minimum insulin-induced hypoglycemia relative to VEH/CON." (PMID 33093533, 2020).
Hypoglycemia (continued). "Therefore, we need to reduce the insulin dosage even more quickly when blood glucose reaches the target to decrease the occurrence of hypoglycemia as much as possible in the future treatment." (PMID 32149152, 2020). "The following year, Fabris and Breton demonstrated that real-time insulin sensitivity estimation for smart bolusing using Kalman filtering could effectively reduce postprandial hypoglycemia in the 4 h period following aerobic exercise." (PMID 32517068, 2020). "At the time of hypoglycemia, the levels of insulin and C-peptide were suppressed." (PMID 32393233, 2020). "Participants were previously treated with basal insulin with or without oral glucose-lowering drugs (excluding insulin secretagogues) and had to fulfil at least one predefined criterion for hypoglycaemia risk." (PMID 31984443, 2020). "Hypoglycaemia was reported with equal frequency in praliciguat- and placebo-treated participants, and, with the exception of a single placebo-treated individual, was observed exclusively in those receiving concomitant insulin therapy." (PMID 31858186, 2020). "We hypothesised that a high flow of carbohydrates through the duodenum and upper jejunum, eliciting a high insulin secretory response, may also induce insulin resistance as a protective mechanism against hypoglycaemia." (PMID 32385603, 2020). "Metformin, best known as a growth inhibitor, induces glucose stabilization, enhances insulin sensitivity and reduces the circulating insulin levels without associated hypoglycemia." (PMID 33212778, 2020). "By comparing AST and ITT, the secretion curves show that GH mean values were statistically higher (p value < 0.01, Bonferroni-corrected α: 0.01) after insulin-induced hypoglycemia all throughout the sample collection, from t30 onwards, till the end of the test." (PMID 33362716, 2020). "Those on supplemental insulin were less likely to develop hypoglycemia (P-value <0.001)." (PMID 32133264, 2020). "A higher release of insulin, in turn, requires a higher insulin inhibition in order to avoid hypoglycemias; this is represented in Sorensen’s model by the dynamics of the inhibitor I (Eq 9), which is made to follow the insulin release X much faster by increasing the value of the parameter β." (PMID 32797106, 2020). "Their insulin levels at the time of hypoglycemia were between 8.3 and 27.7 pmol/L." (PMID 32071842, 2020). "A possible reason for this might have been the severe hypoglycemia occurred in the intravenous insulin treatment group." (PMID 32575739, 2020). "In this study, to reduce the risk of hypoglycaemia, we devised the new SIIT (N-SIIT) simply based on the concept of “treat to target” by stepwise addition or reduction of small units of insulin (basically 2 units of insulin)." (PMID 32005949, 2020). "Beta-cell overgrowth and inappropriate insulin over secretion result in life-threatening hypoglycemia, which may require surgical resection of the hyperplastic region of the pancreas." (PMID 33060578, 2020). "Similarly, there are about 109 beta cells in humans, and tens of mutations can give rise to hypersecreting adenomas, so that potentially lethal hypoglycemia due to insulin-secreting adenomas would seem to be inevitable." (PMID 32433950, 2020). "To summarise, while there is strong evidence that switching from NPH insulin to Gla-300 in patients with T2DM decreases hypoglycaemia risk without causing weight gain, data from randomised controlled trials are inconsistent regarding improvement in HbA1c." (PMID 32337298, 2020). "Accordingly, more and more patients admitted to the ER for hypoglycaemia are on insulin therapy." (PMID 32704570, 2020). "A study reported 33% and 35% incidence of mild and severe hypoglycemia with insulin respectively." (PMID 33403188, 2020). "The occurrence of hypoglycemia in patients with T2DM treated with insulin is well established." (PMID 32151247, 2020).
Hypoglycemia (continued). "An effective treatment option for hypoglycemia in these patients could be to block insulin signalling." (PMID 32157856, 2020). "The absence of ketones (for example, β-hydroxybutyrate) confirms an insulin-replete state as opposed to other causes of non-insulin-mediated hypoglycemia." (PMID 32605595, 2020). "However, there was no significant change in SST-containing terminals contacting GHRH neurons with repeated insulin-induced hypoglycemia." (PMID 33148883, 2020). "CBF increments in response to insulin-induced hypoglycemia may be mediated by adenosine and ATP-sensitive potassium channels (KATP)." (PMID 33277531, 2020). "More recently, these guidelines are now being evaluated through clinical trials on high intensity interval exercise to determine how modifications of basal insulin may be helpful in preventing nighttime and mealtime hypoglycemia." (PMID 32517068, 2020). "Elevated GLP-1 levels clearly enhance insulin secretion but may also lead to beta cell mass expansion, which some researchers believe leads to hyperinsulinemic hypoglycemia after RYGB." (PMID 33287109, 2020). "This is the case of hypoglycemia induced by 2-deoxi-D-glucose or insulin, which activates preferentially A-containing chromaffin cells in contrast to baroreceptor reflex activation or acute and chronic cold exposure, which predominantly stimulates NA-containing chromaffin cells." (PMID 33171955, 2020). "Furthermore, when administered an i.p. bolus of exogenous insulin, SC-alpha-transplanted animals are protected from hypoglycemia." (PMID 32382023, 2020). "Mainly ameliorates the consequences of the disorders rather than the central mechanisms responsible for the autonomic dysfunctions, and the major side effects are bradycardia, hypotension, arrhythmia, or hypoglycemia, and possible hypoglycemia in patients receiving insulin therapy." (PMID 32161563, 2020). "In developing organisms, growth hormone may play an important role in inducing insulin resistance under fasting stress conditions, which may be significant for the defense against hypoglycemia." (PMID 32283715, 2020). "Repeated insulin-induced hypoglycemia blunted the corticosterone response." (PMID 33148883, 2020). "In the case of hypoglycemia, the combination with an insulin pump can stop basal delivery, making Medtronic the first company to offer a commercial near-closed-loop system (satisfaction: 71%, respondents: 3.6%) [User of Medtronic EnliteTM Sensor (satisfaction: 69%, respondents: 17.5%)]." (PMID 33332410, 2020). "Overall, GV variability may be an important target for hypoglycemia prevention and management in diabetic patients treated with insulin." (PMID 32622354, 2020). "Severe hypoglycemia was successfully prevented and measurement of serum levels of insulin and further lab diagnostics were performed much faster, while the patient’s individual burden caused by invasive procedures could be reduced." (PMID 33275114, 2020). "Moreover, day-to-day fasting SMBG variability was also found to be associated with the risk of overall symptomatic, nocturnal symptomatic and severe hypoglycemia in insulin-treated patients with diabetes." (PMID 32622354, 2020). "Patients need to monitor their BG concentration several times a day and carry out consequent therapeutic actions, such as determining insulin doses, or when hypoglycemia is detected, ingesting a small amount of fast-acting carbohydrates (15–20 g), the so-called hypotreatment." (PMID 32664432, 2020). "In patients with T2D and liver cirrhosis, insulin therapy often induces unexpected hypoglycemia." (PMID 33457424, 2020). "The strong stimulatory effect of hypoglycemia might have covered the moderate stimulatory effect of insulin on HPA secretory activity." (PMID 32187262, 2020). "Despite these findings, many of the strategies described and currently in use lack a definitive efficacy, and the insulin release based on glucose-demand may fail, resulting in hypoglycemia." (PMID 32325974, 2020).